TSBP1 (testis expressed basic protein 1)
Synonyms: C6orf10; TSBP
Tractability: Antibody: UniProt predicts a signal peptide or a membrane-spanning region.
Gene: Protein-coding gene on chromosome 6 (32,288,526 to 32,371,907, reverse strand). Ensembl gene ENSG00000204296.
Subcellular location: Membrane
Subcellular location (Human Protein Atlas): Endoplasmic reticulum
Gene Ontology:
Cellular component: nucleus; membrane
Genetic constraint (gnomAD): Loss-of-function variants: 19 observed, 26.16 expected, observed/expected ratio (o/e) 0.73, 90% interval 0.51 to 1.07. The upper end of that interval is the gene's LOEUF score, 1.07, which puts it in group 4 of 6, group 1 being the genes least tolerant of losing a copy. Missense variants: 361 observed, 477.76 expected, observed/expected ratio (o/e) 0.76, 90% interval 0.69 to 0.82. Synonymous variants: 133 observed, 164.4 expected, observed/expected ratio (o/e) 0.81, 90% interval 0.7 to 0.93.
Homologues: Orthologues: macaque TSBP1 (85% identical), chimpanzee TSBP1 (75% identical), rat Tsbp1 (21% identical), mouse Tsbp1 (17% identical).
Diseases named in the same sentence as TSBP1 in open-access papers:
TSBP1 is named in the same sentence as 32 diseases in open-access papers, as found by Europe PMC text mining. Sharing a sentence is not in itself a finding about the gene and the disease. The quoted sentences say what the papers report.
lip (1 paper, 2025). "Novel loci include those mapping to LHX8 and TSBP1 (combined clefts), ARHGEF18 and ARHGEF19 (cleft lip with/without palate), FBN2 (cleft lip only), SLC35B3 (cleft palate only), CASC20 (Pierre Robin Sequence) and CHRM2 (non-syndromic cleft palate only)." (PMID 41075272, 2025).
TSBP1 also shares sentences with these, for which no sentence is quoted: psoriasis (3 papers); rheumatoid arthritis (3); asthma (2); autoimmune disease (2); Hypertension (2); neurodegenerative disease (2); Abdominal obesity (1); Alzheimer disease (1); amyotrophic lateral sclerosis (1); atherosclerosis (1); atopic asthma (1); Autoimmunity (1); Coronary arteriosclerosis (1); diabetes mellitus (1); frontotemporal dementia (1); Graves disease (1); hyperthyroidism (1); hypertriglyceridemia (1); hypogonadism (1); hypothyroidism (1); inflammatory polyarthropathies (1); lung neoplasm (1); metabolic disorders (1); metabolic syndrome (1); multiple sclerosis (1); myocardial infarction (1); Parkinson disease (1); polymyalgia rheumatica (1); schizophrenia (1); systemic lupus erythematosus (1).
A further 1 disease shares a sentence with TSBP1 in 1 paper.